ENSG00000262560 (novel protein)
Gene: Protein-coding gene on chromosome 15 (43,772,617 to 43,799,133, reverse strand). Ensembl gene ENSG00000262560.
Genetic constraint (gnomAD): Missense variants: 131 observed, 128.89 expected, observed/expected ratio (o/e) 1.02, 90% interval 0.88 to 1.17. Synonymous variants: 55 observed, 55.25 expected, observed/expected ratio (o/e) 1, 90% interval 0.8 to 1.25.